CA3 (carbonic anhydrase 3)
Description:
Reversible hydration of carbon dioxide.
Synonyms: Car3; CAIII
Tractability: Small molecule: an approved drug acts on it; a high-quality ligand is known; it has a binding pocket of medium quality; it belongs to a druggable protein family. PROTAC: a small molecule that binds it is known.
Target class: Enzyme; Lyase
Gene: Protein-coding gene on chromosome 8 (85,373,436 to 85,449,040, forward strand). Ensembl gene ENSG00000164879.
Subcellular location: Cytoplasm
Pathways (Reactome):
Metabolism: Reversible hydration of carbon dioxide
Gene Ontology:
Molecular function: carbonate dehydratase activity; protein binding; nickel cation binding; phosphatase activity; zinc ion binding
Biological process: cellular response to hypoxia; cellular response to insulin stimulus; cellular response to leptin stimulus; liver regeneration; negative regulation of apoptotic process; negative regulation of intrinsic apoptotic signaling pathway in response to hydrogen peroxide; negative regulation of reactive oxygen species biosynthetic process; positive regulation of cell population proliferation; response to alcohol; response to ethanol; response to lipid; response to oxidative stress; skeletal muscle contraction
Cellular component: cytoplasm; cytosol; nucleus; sarcomere
Genetic constraint (gnomAD): Loss-of-function variants: 17 observed, 20.99 expected, observed/expected ratio (o/e) 0.81, 90% interval 0.55 to 1.22. The upper end of that interval is the gene's LOEUF score, 1.22, which puts it in group 5 of 6, group 1 being the genes least tolerant of losing a copy. Missense variants: 176 observed, 217.42 expected, observed/expected ratio (o/e) 0.81, 90% interval 0.71 to 0.92. Synonymous variants: 84 observed, 90.42 expected, observed/expected ratio (o/e) 0.93, 90% interval 0.78 to 1.11.
Homologues: Orthologues: chimpanzee CA3 (99% identical), macaque CA3 (97% identical), mouse Car3 (92% identical), dog CA3 (90% identical), guinea pig CA3 (90% identical), rat Car3 (87% identical), pig CA3 (87% identical), rabbit CA3 (85% identical), zebrafish cahz (56% identical), zebrafish ca2 (53% identical), Caenorhabditis elegans cah-5 (37% identical), Drosophila melanogaster CARPB (32% identical), and 12 more. Paralogues in human: CA2 (58% identical), CA13 (58% identical), CA1 (55% identical), CA7 (50% identical), CA5A (46% identical), CA5B (45% identical), CA8 (37% identical), CA12 (33% identical), CA14 (33% identical), CA10 (33% identical), CA6 (33% identical), CA9 (31% identical), and 2 more.
Diseases named in the same sentence as CA3 in open-access papers:
CA3 is named in the same sentence as 73 diseases in open-access papers, as found by Europe PMC text mining. Sharing a sentence is not in itself a finding about the gene and the disease. The quoted sentences say what the papers report.
Obesity (6 papers, 2017 to 2023). Accumulation of substantial excess body fat. "Although the correlations between most of the DEGs we identified in this study and obesity are well-established, such as SERPINE1, PLAUR, CA3, and TIMP1." (PMID 35894174, 2022).
breast carcinoma (2 papers, 2010 to 2023). "CEA is found to be high in malignant pleural effusions related to squamous and adenocarcinoma; CA-3 is found to be high in pleural fluids caused by breast cancer." (PMID 20835307, 2010).
heart failure (2 papers, 2011 to 2024). Inability of the heart to pump blood at an adequate rate to meet tissue metabolic requirements. "These genes included: carbonic anhydrase 3 (Ca3), an enzyme known to contribute to cardiac hypertrophy and heart failure when expressed in the heart; haptoglobin (Hp), a biomarker of inflammation and cardiovascular disease (CVD); and heat shock protein 90 (Hsp90aa1)." (PMID 21338512, 2011).
muscular dystrophy (2 papers, 2012 to 2014). Muscular dystrophy (MD) refers to a group of more than 30 genetic diseases characterized by progressive weakness and degeneration of the skeletal muscles that control movement. "Comparison of the two muscular dystrophy phenotypes, DMD and BMD, in the UNEW cohort revealed again CA3 as an important contributor for the separation of these two patient groups and MDH2 and MYL3 for separation of the BMD patients and female carriers in both blood preparation types." (PMID 24920607, 2014).
achromatopsia (1 paper, 2014). Achromatopsia (ACHM) is a rare autosomal recessive retinal disorder characterized by color blindness, nystagmus, photophobia, and severely reduced visual acuity due to the absence or impairment of cone function. "Further, the hB3 gene was used successfully for retinal gene augmentation therapy to restore cone function in dogs with CNGB3-achromatopsia confirming proper functioning of cA3+ hB3 channels." (PMID 24586388, 2014).
chordoma (1 paper, 2010). Chordomas are rare malignant tumors arising from embryonic remnants of the notochord in axial skeleton. "For cell lines that lack Brachyury but have abnormal genetics (like CM319), expression of one or more markers of chordoma including CD24, collagen type II alpha 1, keratin 19, and carbonic anhydrase 3 could offer evidence of chordoma-derived cells." (PMID 21253487, 2010).
disc degeneration (1 paper, 2025). "Carbonic anhydrase 3 (CA3) and glucose transporter 1 (GLUT1) are known NP phenotypic markers whose abundance decreases during disc degeneration and aging." (PMID 40585254, 2025).
fibrosis (1 paper, 2020). the formation of excess fibrous connective tissue in an organ or tissue in a reparative or reactive process. "The analysis of the nine genes, namely A2m, Akr7a3, Aqp7, Ca3, Cdc2a, Cdkn3, Cyp2c11, Ntf3, and Sds, revealed the association between NGHCs and chronic inflammatory liver conditions, including liver cirrhosis and fibrosis." (PMID 32560183, 2020).
ischemic stroke (1 paper, 2024). A stroke disorder caused by obstruction of blood flow to the brain, due to thrombotic (local blood clot formation) or embolic (due to a blood clot or other material traveling from another site) event. "DEPs, including GNAQ (G protein subunit α Q), CA3 (carbonic anhydrase 3), ARL6IP5 (ADP ribosylation factor like GTPase 6 interacting protein 5), and SPTB (spectrin β) were identified in total participants between recurrence and nonrecurrence patients with ischemic stroke." (PMID 38420847, 2024).
keloid (1 paper, 2013). An irregularly shaped, elevated mark on the skin caused by deposits of excessive amounts of collagen during wound healing. "Decreased levels of carbonic anhydrase-3 gene transcripts were observed in this study with electrosurgery incisions, as has been seen for carbonic anhydrase protein isoforms in recalcitrant keloid scar tissue." (PMID 24058457, 2013).
legionellosis (1 paper, 2020). Any disease caused by Legionella bacteria. "The results revealed three up-regulated genes (SEC22B, CXCL2, and CYCS) and two down-regulated genes (CA3, CA4) were significantly involved in Legionellosis and nitrogen metabolism pathways, respectively." (PMID 32174961, 2020).
lung carcinoma (1 paper, 2017). "Levels of creatine kinase, but not carbonic anhydrase-3, were shown to be decreased in diaphragm and vastus lateralis of patients with severe COPD and lung cancer cachexia." (PMID 29255650, 2017).
mesenchymal tumors (1 paper, 2010). "Five genes were significantly differentially expressed in chordoma tumors compared with three control groups (nonchordoma mesenchymal tumors, normal tissues, and IVD): T, CD24, COL2A1, CA3, and KRT19." (PMID 21253487, 2010).
myasthenia gravis (1 paper, 2023). Myasthenia gravis (MG) is a rare, clinically heterogeneous, autoimmune disorder of the neuromuscular junction characterized by fatigable weakness of voluntary muscles. "CHRNA1 homeostasis is vital for postsynaptic signal regulation, and altered CHRN endocytosis mediated by carbonic anhydrase 3 might contribute to the pathogenesis of myasthenia gravis." (PMID 37542348, 2023).
tumor (10 papers, 2012 to 2024). "After primary breast cancer was treated with doxorubicin, but not cisplatin, CAFs in the lung secrete complement factors such as Ca3 and Ca5 to recruit myeloid-derived suppressive cells to modulate the immunosuppressive metastatic niche (the soil) for circulating tumor cells (the seedlings)." (PMID 37173915, 2023). "The genes TIMP1, MAGEB17, CA3, and KRT75 expressions are relatively lower with sequence read at <100 in both cultured cells and tumor samples." (PMID 33808801, 2021).
infection (3 papers, 2010 to 2025). The state of being infected such as from the introduction of a foreign agent such as serum, vaccine, antigenic substance or organism. "The genes that were down-regulated at 48 hours post-infection include carbonic anhydrase 3 and guanidinoacetate methyltransferase, both of which are known to be down-regulated in response to liver injury." (PMID 20082697, 2010). "Whereas no signalling role has yet been ascribed to cA5, cA3 has been demonstrated to activate a family of DNases termed NucC which abort infection by degrading the host genome prior to completion of the phage replication cycle." (PMID 32338598, 2020).
bacterial infection (1 paper, 2008). "Of these, only 3 genes (CA3, KRT17 and PLN) have been annotated, and none of these previously have been shown to be involved in the response to bacterial infection." (PMID 18811943, 2008).
CA3 also shares sentences with these, for which no sentence is quoted: cancer (10 papers); hepatocellular carcinoma (5); type 2 diabetes (5); diabetes (4); Insulin resistance (3); cholestasis (2); cognitive decline (2); Duchenne muscular dystrophy (2); fatty liver (2); myocardial infarction (2); type 1 diabetes (2); acute myocardial infarction (1); adenocarcinoma (1); adrenal cancer (1); anaemia (1); Anxiety (1); atrial fibrillation (1); autoimmune disease (1); Becker-type muscular dystrophy (1); Cachexia (1); cardiac hypertrophy (1); cardiovascular disease (1); cerebral malaria (1); cerebrovascular disease (1); cognitive disorder (1); colitis (1); colon carcinoma (1); dementia (1); Dent disease type 1 (1); diabetic kidney disease (1).
A further 26 diseases each share a sentence with CA3 in 1 paper.